GSK3B (glycogen synthase kinase 3 beta)
Diseases named in the same sentence as GSK3B in open-access papers (continued):
Sharing a sentence is not in itself a finding about the gene and the disease.
cancer (continued). "Understanding of how GABABR, GSK‐3β, and NF‐κB participate in the CRC cell proliferation and cell cycles will be helpful in finding deep regulation mechanism of cancer cell in order to facilitate clinical application." (PMID 27060477, 2016). "Anactivated Akt pathway is a canonical metastasis marker in many cancers, and inducesepithelial-mesenchymal transition (EMT) by inhibiting GSK-3β, leading to the stabilization and nuclear localization of Snail, thereby triggering cell migration and EMT." (PMID 27119355, 2016). "Further, inactivation of GSK-3β can upregulate β-catenin during gastrin and TNF-α induced EMT of cancer cells." (PMID 27058759, 2016). "Since GSK3β is known to be inactivated by AKT or ERK, our work suggests a direct role of the GSK3β-EZH2 pathway in this scenario and offers a rationale for enhancing GSK3β activity and/or targeting EZH2 in anti-cancer therapy." (PMID 27494834, 2016). "In particular, GSK-3β is a key member in the GSK-3β/β-catenin pathway, which is suspected as a major sub-pathway of "pathways in cancer"(hsa05200)." (PMID 27045586, 2016). "Hes1 binds to the Bmi-1 locus and upregulates Bmi-1expression, which consequently downregulates PTEN and activates the Akt/GSK3β pathway, induces EMT and cytoskeleton reconstruction, ultimately leads to enhanced invasiveness of cancer cells." (PMID 26452029, 2015). "Our present study showed that SMA fulfils anti-cancer agent criteria for inhibiting genetically heterogeneous cancers by inhibiting both PI3K/Akt and tankyrase, which is a regulatory component of GSK3β activity." (PMID 26544726, 2015). "The results indicated that RKIP inhibited ERK, NF-κB, and Stat3 signaling, and activated GSK-3β signaling in NPC cells, which is consistent with the previous reports in the other types of cancers." (PMID 25915430, 2015). "MACF1 has no direct relation with cancer, it has been reported to function in the Wnt signaling pathway and to be associated with a complex containing Axin, beta-catenin, glycogen synthase kinase 3 (GSK3B), and adenomatous polyposis coli (APC), which have been linked to tumorigenesis." (PMID 24622401, 2014). "Previous findings with other GSK-3β inhibitors (e.g. LiCl, TDZD8) in subcutaneously xenografted cancer cells further support this notion." (PMID 25344861, 2014). "The GSK-3β-dependent phosphorylation of LCRMP1 positively regulates filopodia formation, migration and cancer cell invasion." (PMID 24765134, 2014). "A number of studies have shown that the activated AKT/GSK-3β pathway participates in the EMT process and contributes to the aggressive phenotype and chemoresistance in several human cancers." (PMID 24944676, 2014). "Taken together, our study has identified Akt/GSK-3β and mTOR as important targets of DHC and has thus highlighted its potential application in angiogenesis-related diseases, such as cancer." (PMID 22359572, 2012). "Here, we showed that GSK3β-dependent phosphorylation of LCRMP-1 positively regulates filopodia formation, migration and cancer cell invasion." (PMID 22363707, 2012). "Here, we demonstrated that GSK3β can phosphorylate LCRMP-1 and modulate filopodia formation, cancer cell migration and invasion." (PMID 22363707, 2012). "We found that a combined treatment of LY294002 and SB-216763 improved the cytotoxic effect against UMUC-3 and UMUC-14 carcinoma cells over LY294002 alone, suggesting potential therapeutic uses for GSK-3β inhibitors." (PMID 21864408, 2011).
cancer (continued). "Although negative kinase regulators that antagonize the activity of GLI transcription factors have been reported, including GSK3β, PKA and CK1s, little is known regarding positive kinase regulators that are suitable for use on cancer therapeutic targets." (PMID 19575820, 2009). "In contrast, GSK3B inhibition did not significantly affect sensitivity of cancer cells to IR-induced killing in MCF7 and U2OS cells (data not shown)." (PMID 41243969, 2025). "Moreover, genes related to cancer therapeutic targets, such as ABCG2, GSK3B, PTCH1, STAT3 and WEE1, were also upregulated." (PMID 39726234, 2025). "Activated AKT also controls GSK3β, subsequently augmenting MYC activity in cancer cells." (PMID 40027648, 2025). "The study lacks functional validations of downstream PI3K/AKT regulators (e.g., GSK-3β, mTOR, FOXO proteins) and rescue experiments using AKT activators to further delineate the mechanistic link between PI3K/AKT inhibition and ferroptosis in cancer therapy." (PMID 40732297, 2025). "Furthermore, the dual inhibition of GSK3β and the PI3K/mTOR pathway has been investigated as a potential therapeutic strategy in cancer." (PMID 41190025, 2025). "While aspirin alone does not trigger apoptosis, it inhibits GSK-3β activation and downregulates its targets (cyclin D1, Bcl-2), which are involved in cancer cell survival and chemoresistance." (PMID 40649990, 2025). "In addition to the receptors FGFR1, FGFR4 and ERBB4, the main effector AKT1 and its downstream effectors, MTOR, GSK3B, p21, WEE1, BAD and CREB5, which mediate cancer cell growth and progression, also exhibited marked changes in HPV-ind CCs." (PMID 38253702, 2024). "In LoVo cells, Hsu and colleagues reported that TQ (5, 10, and 20 μM) suppressed the expression of proteins critical for cancer progression, including COX-2, PI3K, AKT, and glycogen synthase kinase-3 beta (GSK-3β), with the strongest reduction observed at 20 μM." (PMID 39769996, 2024). "Additionally, LINC01405 upregulation led to the increased cell populations, proliferation, and upregulation of critical cancer‐related genes, including AKT1, AKT3, mTOR, WNT3A, SMAD3, CYCLIN D1, CYCLIN D2, BCL2, and GSK3B." (PMID 38225865, 2024). "PIWIL1 and PIWIL2 play similar roles in activating the PI3K-AKT signaling pathway to phosphorylate and inactivate GSK3β and promote the stability of CLOCK and BMAL1 by repressing GSK3β-induced phosphorylation and ubiquitination of these two proteins in cancer cells." (PMID 38473819, 2024). "These pathways may be inhibited (GSK-3β 16) or activated (Notch1 10, SRC 15) by ASPH in a cell type-specific manner, leading to heterogeneous responses to ASPH inhibition in different cancer cell lines." (PMID 38817852, 2024). "Moreover, we identified the miR-26a-1-3p site in the 3′ untranslated region (UTR) of GSK3β, MYC, and CCND1 mRNA, thus predicting a link between miR-26a and Met/GSK3β/MYC/CCND1 in cancers." (PMID 36672275, 2023). "mTOR is frequently upregulated in cancers, and mTOR overexpression could also block the mPTP opening to the same extent as activating AKT and inactivating GSK3β." (PMID 36982637, 2023). "For GP5, CDK12 inactivation and gains of AKT1, GSK3B, PIK3CA, CCND1, and MDM2 were identified as the top truncal druggable targets that would be most likely to obtain a durable response due to their presence in all cancer cells." (PMID 37828555, 2023). "Altogether, these results suggest that 5α-reductase inhibition may decrease cancer cell progression and migration via p21, Bcl-2, MMP2, MMP9, NF-κB, and GSK3β signaling pathways." (PMID 36800968, 2023). "However, according to previous studies, GSK3B or CSNK1, which belong to the β-catenin destruction complex, which inhibits activation of β-catenin signaling, can paradoxically induce or aggravate cancer." (PMID 37149563, 2023).
cancer (continued). "Importantly, as different molecular pathways—such as the MAPKs, GSK3β, βTRCP, PI3K, AKT pathway—regulate NRF2 expression in cancer cells, future investigations are needed to elucidate the main mechanism involved in NRF2 availability in GBM." (PMID 37189700, 2023). "Additionally, 1-Azakenpaullone is an inhibitor of glycogen synthase kinase-3 beta (GSK-3β), which is a tempting target for cancer treatment." (PMID 38139172, 2023). "GSK-3β’s pathological role is marked by upregulation of expression and activity in cancer cells compared to non-neoplastic cells and defined by differential phosphorylation." (PMID 36430630, 2022). "Glycogen synthase kinase 3β (GSK3β) is a serine/threonine kinase that participates in a variety of signal transduction cascade reactions, inducing the EMT and regulating the expression of multiple cancer-related transcription factors." (PMID 36365233, 2022). "However, the expressions of CUL3, GSK3B, KEAP1, and MAPK9 showed positive relationship with RNAss in various cancers." (PMID 35242279, 2022). "Recently, Sarah Riis and colleagues reported a conserved Akt/GSK-3β/Nrf2/BNIP3 pathway for regulating mitochondrial morphology and dynamics in mouse embryonic fibroblasts and cancer cells, which provides mechanistic clues for IGF-1-dependent BNIP3 transcription during differentiation." (PMID 35334906, 2022). "In addition to regulating ion transport, WNKs are associated with other signaling pathways that play critical roles during cancer progression, including Akt, MAPK, TGF-β, GSK3β, and Wnt signaling pathways." (PMID 36123332, 2022). "In cancers, the hyper‐activation of FGFR4 signalling is a common alteration leading to the activation of various intracellular pathways, including GSK3β/β‐catenin/E‐cadherin, FGFR4–GSK3b–Nrf2 signalling and PI3K‐AKT." (PMID 35194944, 2022). "However, in some cancer types, including AML, inactivated GSK-3β (through increased Ser9 phosphorylation) leads to the opposite outcome where it has been associated with low overall survival of patients." (PMID 35669422, 2022). "Not surprisingly, the GSK-3β/β-catenin pathway is involved in the progression and invasiveness of many types of cancers." (PMID 36293057, 2022). "The effects of GSK-3β inhibitors combined with radiotherapy and chemotherapeutics on a variety of cancers have been reported, indicating that GSK-3β will play an important role in cancer treatment." (PMID 35836256, 2022). "The reduction in DNMT1 activity by inhibiting GSK3β-mediated phosphorylation of DNMT1 resulted in the re-expression of hormone receptors AR and ER in PCa and BCa cells, respectively, and re-sensitized these cancers to antihormones." (PMID 35402240, 2022). "We isolated palmitoylated proteins from GBM cells with ABE and identified many cancer-driving genes using mass spectrometry, among which GSK3β has not been reported." (PMID 35606353, 2022). "When GSK3β is inhibited by AKT, free β-catenin accumulate and translocate to the nucleus, ultimately activating downstream target genes such as cyclin D1, C-Myc, CD44, FN1, C-JUN, Slug, L1CAM, and MMP14; thus contributing to tumorigenesis and EMT of cancer." (PMID 34546849, 2021). "Polyphenol resveratrol, apart from causing endoplasmic reticulum stress that has already been mentioned, inhibits both Akt and ERK, thus facilitating GSK3β reactivation on OVCAR3 cell line, with a consequent lower expression of cyclin D1 and reduced cancer cell number." (PMID 32767962, 2021). "Although multiple GSK-3β inhibitors are currently under preclinical and clinical evaluation, no compound has yet been approved for cancer treatment." (PMID 33572396, 2021). "It has been shown that highly active Akt does not fully inhibit GSK3β activity in some cancers and cancer cell lines." (PMID 34064046, 2021).
cancer (continued). "For this reason, we focused on four MYC-interacting proteins, i.e., Promyelocytic leukemia protein (PML), Glycogen synthase kinase-3 beta (GSK3B), Cyclin-Dependent Kinase Inhibitor 2A (CDKN2A), and Histone deacetylase 2 (HDAC2), which were reported to be mis-regulated in cancer in previous studies." (PMID 36303724, 2021). "The general anti-cancer mechanisms of cordycepin are regulated by the adenosine A3 receptor, epidermal growth factor receptor (EGFR), mitogen-activated protein kinases (MAPKs), and glycogen synthase kinase (GSK)-3β, leading to cell cycle arrest or apoptosis." (PMID 34443541, 2021). "ZVI-NP triggered ferroptosis selectively in cancer cells by suppressing NRF2-mediated cytoprotection program, which was attributed to the ZVI-NP-induced disruption of AMPK/mTOR signaling and activation of GSK3β/β-TrCP-dependent degradation system." (PMID 34093872, 2021). "Flow shear may promote the EMT process and render cancer cells to be more aggressive by activating embryonic-like stem properties through the deactivation of ERK and GSK3β." (PMID 33585411, 2020). "This is probably because GSK3β activity is finely controlled by a balanced, differential phosphorylation of its S9 and Y216 residues, unlike many cancer types where the activity is deregulated by an excess of Y216 over S9 phosphorylation." (PMID 32503133, 2020). "GSK3β inhibition prevents IFNγ-induced IDO, including in cancer cells, and dendritic cells." (PMID 33375613, 2020). "DEX induced dephosphorylation of GSK-3β and upregulation of c-FLIP(L) in all tested cancer cells." (PMID 33050333, 2020). "However, it should be noted that inhibiting GSK3B alone can also play a pro-cancer role, promoting epithelial to mesenchymal transition (EMT; a measure of metastatic potential) and cancer stemness (a measure of resistance to chemotherapy)." (PMID 32698955, 2020). "Accordingly, we proposed that the Akt/GSK-3β axis may be involved in the LDOC1-mediated suppression of IL-1β production and anti-cancer effects in OSCC." (PMID 33120999, 2020). "GSK3β is very rarely altered at the genomic level in cancers, therefore pharmaceutical inhibition of GSK3β is not expected to be specific for cancer cells." (PMID 32850361, 2020). "In addition, we also examined the effect of DEX on GSK-3β activation and upregulation of c-FLIP(L) protein in other cancer cells." (PMID 33050333, 2020). "Based on the involvement of ASPH in Wnt signaling and cellular senescence in various cancers, we hypothesized that ASPH was involved in the bone formation and cellular senescence through regulating Gsk3β and β-catenin." (PMID 33015050, 2020). "The flow shear may promote the EMT process and render cancer cells to be more aggressive by activating embryonic-like stem properties through the deactivation of extracellular signal-regulated kinase (ERK) and GSK3β." (PMID 33585411, 2020). "In addition, RUNX1-IT1/miR-632/GSK-3β cascades also participated in modulation of EMT and cancer stem traits of HCC cells under hypoxic conditions (P < 0.01)." (PMID 32024815, 2020). "In addition, GSK-3β can mediate the efficacy of RUNX1-IT1 on cell proliferation, EMT and cancer stem-like properties in HCC cells (P < 0.05)." (PMID 32024815, 2020). "The possibility remains that GSK-3β inhibition to suppress cancer growth involves a different mechanism independent of the canonical Wnt pathway, and this requires further investigation." (PMID 31698687, 2019). "The contribution of GSK3β and USF2 to carcinogenesis also seems to be influenced by the cellular context, although the majority of studies point to a cancer-promoting effect where, like in the present study, GSK3β activated USF2 promoted proliferation and cell migration." (PMID 31013770, 2019). "Since GSK3-β knock down increased Chk1 phosphorylation and activation, we hypothesized that combined GSK3-β and Chk1 inhibition may exert synergistic anti-cancer activity." (PMID 31362447, 2019).
cancer (continued). "In addition, in cancer samples with low CDK5RAP3 protein levels, the proportion of samples exhibiting p-GSK-3β (Ser9) expression was also significantly higher than that exhibiting high CDK5RAP3 expression (64.0% vs. 32.0%)." (PMID 29540196, 2018). "Recently, some studies have indicated that GSK-3β can regulate autophagy; however, others suggest that the regulatory effects of GSK-3β are not the same in different cancers." (PMID 29793508, 2018). "In addition, we demonstrated that the overexpression or knockdown of KRT19 regulated cancer stem cell reprogramming by modulating the expression of cancer stem cell markers (ALDH1, CXCR4, and CD133) as well as the level of p-Src and p-GSK3β (Tyr216)." (PMID 29747452, 2018). "As PI3K/Akt/GSK-3β signaling pathway plays an important role in promoting the process of EMT and mediating the metastasis of cancer, and PTEN can act as a phosphatase to dephosphorylate Akt, so we detected the expression of the key members in this PTEN-Akt-GSK-3 signaling molecules." (PMID 30108501, 2018). "Furthermore, miR-106b-5p promotes the progression of CC by targeting three key genes (GSK3B, VEGFA, PTK2) through three crucial pathways (PI3K-Akt signaling pathway, focal adhesion, and pathways in cancer)." (PMID 30275981, 2018). "KRT19 regulated cancer stem cell reprogramming by modulating the expression of cancer stem cell markers (ALDH1, CXCR4, and CD133), as well as the phosphorylation of Src and GSK3β (Tyr216)." (PMID 29747452, 2018). "These modulations may be partially due to the alteration of cancer stem cell markers (ALDH1, CXCR4, and CD133) expression as well as the phosphorylation of Src and GSK3β (Tyr216)." (PMID 29747452, 2018). "Collectively, this study sheds light on a novel mitotic function of GSK3β in the regulation of TPR-dynein mediated centrosome homeostasis, which may facilitate the discovery of new treatment regimens for cancer targeting mitosis." (PMID 29568361, 2018). "Therefore the in vivo anti-cancer activity of AQTGTGKT peptide results from its effect on the expression of and cyclinD1 and the binding of CAGE to GSK3β." (PMID 28099142, 2017). "Cancer cells exposed to cytotoxic agents may initiate protective autophagy by activating AMPK, GSK3β, ERK1/2 and eEF2K pathways, and autophagy inhibition may enhance the cytotoxicity of anti-cancer agents." (PMID 28978086, 2017). "OPN secreted by TM4SF4/GSK3β/β-catenin signaling activated the JAK2/STAT3 or FAK/STAT3 pathway, which also up-regulates OPN expression in an autocrine manner and consequently maintains the self-renewal and metastatic capacity of cancer cells." (PMID 29254164, 2017). "Thus, in hypoxic tumors, HIF-1α regulates many genes involved in cancer development and SPHK-1 regulates and stabilizes HIF-1α through the AKT/GSK-3β pathway." (PMID 28165392, 2017). "Our results suggest that DKC-E70 may downregulate cyclin D1 as one of the potential anti-cancer targets through cyclin D1 degradation by T286 phosphorylation dependent on ERK1/2, p38 or GSK3β, and cyclin D1 transcriptional inhibition through Wnt signaling." (PMID 28870200, 2017). "The complexities of GSK-3β function and interactions with PI3K/AKT/mTOR signaling, cell cycling, and apoptotic pathways are poorly understood in the context of lymphomagenesis and cancer therapeutics." (PMID 29383130, 2017). "AKT activation could elevate GSK3β phosp-horylation, which in turn induces Wnt signaling activity and promotes EMT in human cancers." (PMID 28977927, 2017). "In fact, recent studies reported that CB suppresses cell proliferation and induces cell cycle arrest and apoptosis through downregulation of p-ERK, c-MYC, p-GSK-3β, NK-κB/p65, and p38 MAPK, but upregulation of intracellular free calcium ([Ca2+]i) and Cyclin A in cancer cells." (PMID 26959116, 2016).